CTNNB1 (catenin beta 1)
Diseases named in the same sentence as CTNNB1 in open-access papers (continued):
Sharing a sentence is not in itself a finding about the gene and the disease.
breast carcinoma (continued). "Public data analysis from breast cancer patients revealed post-radiotherapy upregulation of the β-catenin pathway, with elevated CTNNB1, MYC, and CD44 expression, alongside reduced CDKN2A and CDH1 levels, supporting clinical relevance." (PMID 40657369, 2025). "ESR1, BRCA1, CTNNB1, and BAX was associated with breast cancer cells proliferation, we further employed Ki67 immunohistochemical staining to evaluate tumor cell proliferation." (PMID 39045563, 2024). "For example, although Apc1638N;Ctnnb1+/-mice were less prone to GI cancers, Apc1638N;Ctnnb1+/- female animals tended to grow breast cancers." (PMID 39320349, 2024). "Our results strongly suggest that PTCH1 and CTNNB1 can be used as robust and cost-effective predictors in developing countries to guide decisions on chemotherapy in ER +/HER2- breast cancer patients with a high risk of recurrence." (PMID 37700842, 2023). "For example, decreased expression CTNNA1 and CTNNB1 corresponds to the progression of in situ breast carcinoma to invasive carcinoma." (PMID 36741258, 2023). "The hydrogels prepared with alginate and chitosan polymers were prepared to deliver the shRNA-encoding plasmid (pshRNA) to MDA-MB-231 cells for the inhibition of β-catenin (CTNNB1), which was reported to be overexpressed in breast cancer." (PMID 37504420, 2023). "In the current study, we revealed a feedback loop formed by miR-182-5p/CMTM7/CTNNA1/CTNNB1/TCF3 in breast cancer progression." (PMID 36829181, 2023). "Lastly, Cox Proportional Hazards Regression put forward PTCH1 and CTNNB1 as key markers of resistance to neoadjuvant therapy in ER+/HER2- breast cancer." (PMID 37700842, 2023). "The hazard ratios for PTCH1, and CTNNB1 in three different arms of treatment in ER+/HER2- breast cancer patients." (PMID 37700842, 2023). "The expression of lncRNA MALAT1 is associated with ERAT1 breast tumors and lower recurrence-free survival (RFS), and lncRNA MALAT1 can promote the occurrence and development of breast cancer by up-regulating the WNT/W-catenin (CTNNB1) pathway." (PMID 35706002, 2022). "First, for some recurrent mutations, such as those from CTNNB1, CSF1R, JAK2, HRAS, and RUNX1, an exhaustive literature search showed that the clinical significance in breast carcinoma has rarely been addressed." (PMID 34203389, 2021). "For example, only FZD7 is consistently found to signal through CTNNB1/TCF in human breast cancer cells, thereby affecting cell proliferation." (PMID 32083079, 2020). "In breast cancers, the members of the Wnt signaling family are rarely mutated: APC (1.3%), CTNNB1 (0.2%), AXIN1 (0.4%), LRP6 (0.7%), LGR5 (0.6%), TCF7L2 (0.3%), and FBXW7 (1.5%)." (PMID 32210163, 2020). "Clinical evidence suggests that WNT/CTNNB1 signaling is elevated across multiple subtypes of human breast cancer." (PMID 32083079, 2020). "Cadherin-1 and Catenin beta-1 have been already shown to interact with p140Cap in human breast cancer MCF7 cells." (PMID 31681758, 2019). "Other findings support a potential role of RASSF1C as oncogene, promoting beta-catenin (CTNNB1) accumulation in HeLa cells and proliferation of lung cancer cells, supporting cell migration and attenuated apoptosis in breast cancer." (PMID 31323949, 2019). "Included in those proteins found to interact with p140Cap, E-cadherin and the Catenin beta-1, have been already found associate to p140Cap by co-immunoprecipitation experiments in MCF-7 cells, a typical luminal A breast cancer model." (PMID 31681758, 2019).
breast carcinoma (continued). "GSK3B and CTNNB1 are highly expressed in bladder cancer and breast cancer, and they are notably positively correlated." (PMID 30181805, 2018). "There are 7 genes in this subnetwork, of which three genes (“GSK3B”, “CTNNB1”, “PIK3CA”) are associated with breast cancer." (PMID 30598085, 2018). "Those include basal-like and luminal-like subgroups, which are reminiscent of breast cancer, as well as a third subgroup, namely CTNNB1-enriched, which is reminiscent of CTNNB1-enriched liver cancer." (PMID 26431491, 2015). "Therefore, indirect regulatory mechanisms likely represent the predominant pathway through which PAEs promote breast cancer progression via CTNNB1." (PMID 41155171, 2025). "CTNNB1 expression was also found upregulated in ER+/HER2- breast cancer." (PMID 41155171, 2025). "Analysis of the TCGA breast cancer datasets revealed that IL8 levels were positively correlated with β-CATENIN (CTNNB1) levels, indicating that the expression of IL8 might be regulated by β-CATENIN signaling." (PMID 36915147, 2023). "However, CTNNB1 was down-regulated in ER+/HER2- breast cancer patients with incomplete pathological response to taxane-based chemotherapy in the validation cohort." (PMID 37700842, 2023). "Therefore, our results suggested the involvement of CTNNB1 in resistance to taxane-based neoadjuvant chemotherapy in ER+/HER2- breast cancer patients." (PMID 37700842, 2023). "A feedback loop formed by miR-182-5p/CMTM7/CTNNA1/CTNNB1/TCF3 may play a critical role in breast cancer." (PMID 36829181, 2023). "In fact, there have been proposals for targeting CTNNB1 as the main player in the WNT canonical pathway in breast cancer as with 3,6-dihydroxyflavone in MDA-MB-231 cell line, even though many unknowns remain." (PMID 37289551, 2023). "YTHDF3 promoted translation of CTNNB1, contributing to proliferation, migration, and maintenance of cancer stem–like properties in ocular melanoma, and mediated breast cancer brain metastasis through increasing m6A-dependent ST6GALNAC5 and epidermal growth factor receptor expressions." (PMID 36183833, 2022). "Although Wnt signaling was first described as inducing breast tumors in mice and Wnt/β-catenin signaling is activated in a proportion of multiple subtypes of human breast cancers, the typical mutations in components of the pathway found in CRC (APC, CTNNB1, AXIN2) are rare in breast carcinomas." (PMID 33227961, 2020). "From these analyses it has been known for a long time that elevated intracellular levels of CTNNB1, a hallmark of active WNT/CTNNB1 signaling, can be detected by immunohistochemistry in a significant (13–77%) proportion of all ductal and lobular breast cancer samples." (PMID 32083079, 2020). "So far, AXIN2 appears to be one of the few universal target genes that could be used to reliably measure relative WNT/CTNNB1 signaling activity in human breast cancer." (PMID 32083079, 2020). "Again, the identification of Kras and Ctnnb1 as recurrently mutated metastasis drivers was unanticipated due to the lack of association with primary tumour biopsies of human breast cancer." (PMID 32463822, 2020). "Wnt pathway activity scores were normal in the reference (WT), increased in loss-of-function APC-mutated ovary cancer and in gain-of-function CTNNB1 Asp32Tyr mutated breast cancer, and normal in non-functionally mutated CTNNB1 Asp665Glu breast cancer." (PMID 33613616, 2020). "Most of what we know about WNT signaling in mammary gland biology and breast cancer comes from studies in mice, where both CTNNB1-dependent and -independent signaling are essential for mammary gland development, branching morphogenesis and function during embryogenesis and in postnatal life." (PMID 32083079, 2020). "Compared to the other anatomic sites, and taking available sample sizes into account, mutations were more prevalent for CDH1 in breast cancer and for CTNNB1 in endometrial cancer, though still not a large proportion of carcinomas at these sites." (PMID 29156750, 2017).
breast carcinoma (continued). "Genetic mutations of APC or the β-catenin encoding gene CTNNB1, which are the major causal factors for hepatic and colorectal cancers, are not typically associated with breast cancer." (PMID 27420097, 2016). "Approximately 6% of breast tumors contain mutations in the APC gene and thus far there are no reports indicating CTNNB1 mutation in cases of breast cancer." (PMID 27420097, 2016). "In line with our data on differential regulation of CTNNB1 in BRCA1 deficient HCC3153 either expressing both TRα and TRβ or just expressing TRβ (i.e. silenced for THRA) further supports an opposing role of TRs in breast cancer." (PMID 26029931, 2015). "We also included CTNNB1 in the analysis since CTNNB1-related signatures were enriched in ER+/HER2- breast cancer patients resistant to taxane-based therapy and high expression of CTNNB1 was associated with decreased survival in ER+/HER2- breast cancer patients." (PMID 37700842, 2023). "The predictions revealed that the mechanism of sinapic acid in breast cancer may be due to regulation of multiple proteins like CTNNB1, PRKCA, CASP8, SIRT1, and cytochrome enzymes (CYP1A1 & CYP3A4); the majorly regulated pathway was predicted to be ‘Pathways in cancer’." (PMID 38081857, 2023). "The adherens junction pathway contains CTNNB1 (gene encoding β-catenin protein), which further supports that DEPDC1B may participate in the wnt/β-catenin signaling pathway in breast cancer cells." (PMID 37642235, 2023). "However, as previously observed in breast cancer, the expression of nuclear β-catenin occurs in the absence of CTNNB1 mutations in our 13 cases." (PMID 36292090, 2022). "Given that the activation of cGMP/PKG signaling has been reported to suppress oncogenic Wnt/β-catenin signaling in colon and breast cancer cells by inhibiting β-catenin expression at mRNA level and β-catenin/CTNNB1 promoter levels, a similar mechanism may exist in lung tumor cells." (PMID 29050202, 2017). "For association analyses of germline variants with breast cancer susceptibility, the results showed that rs7200690, rs7198799, rs17715799, rs13689 and diplotype CGC/TGC (rs7200690 + rs12185157 + rs7198799) in CDH1 as well as rs2293303 in CTNNB1 were associated with increased breast cancer risk." (PMID 26285011, 2015). "CTNNB1 and three additional core genes form a signaling cascade with MYC, amplifying pro-proliferative signaling in breast cancer cells." (PMID 40924735, 2025). "We identified a feedback loop with the composition of miR-182-5p, CMTM7, CTNNA1, CTNNB1 (β-catenin), and TCF3, which play essential roles in breast cancer progression." (PMID 36829181, 2023). "Among different subgroups in breast cancer scRNAseq data, significant correlations between EMP1/COL3A1 and three EMT genes (CDH1, VIM, and CTNNB1) were found in c16 fibroblasts." (PMID 38187400, 2023). "Our independent analysis of primary ER+PIK3CA-mutant breast cancers, which exhibit high INPP4B expression, identified these and additional upregulated Wnt genes (LEF1, MYCN, FZD7, SFRP2, TCF7L1, CTNNB1, FZD4, and SFRP1)." (PMID 34035258, 2021). "We thus examined the relationship between the mRNA expression levels of TGFB1 (TGFβ), CTNNB1 (β-catenin), SNAI1, SNAI2 and ZEB1 and those of Sipa1 in TCGA breast cancer patient samples." (PMID 32193333, 2020). "Overall, almost all the EMT genes analyzed were downregulated in breast cancer samples compared to normal breast tissues, except for CDH1, CTNNB1, and CDH2 that were upregulated in BC." (PMID 32911851, 2020). "Module 3 (4 genes) included regulation of cellular response to stress (BRCA1, CTNNB1, HSP90AA1, and WNT1) and breast cancer (BRCA1, CTNNB1, and WNT1)." (PMID 31608105, 2019). "However, no or very few CTNNB1 mutations have been reported in breast cancer." (PMID 31462314, 2019).
breast carcinoma (continued). "In the current study, we successfully targeted dysregulated CTNNA1, CTNNB1, TLN1, VCL, PXN, and ACTN1 genes by delivering respective siRNAs with the help of nano-sized CA particles in breast cancer cells as well as in a murine breast cancer model." (PMID 31269666, 2019). "Our results have shown the expressional association and clinical relevance of six genes (CDH2, FN1, CITED2, CTNNB1, and CTNNA3) together with GRHL2 for breast cancer metastases." (PMID 23441166, 2013). "Training on public gene expression profiles of 995 breast cancer patients, this method prioritized one gene-set pair (GRHL2, CDH2, FN1, CITED2, MKI67 versus CTNNB1 and CTNNA3) from all 2717 possible gene-set pairs (GSPs)." (PMID 23441166, 2013). "In this study, various breast cancer cell lines and endometrial cells were used to analyze different expression levels of multiple target antigens (EGFR, FOLR1, HER2, EpCAM, NG2, ANK3 and CTNNB1) through flow cytometry and fluorescence microscopy." (PMID 40422194, 2025). "In breast cancer, HOTAIR mediates autophagy progression through interactions matrix metallopeptidases, which are critical for cancer invasion; CTNNB1/β-catenin (catenin beta 1) may play a significant role in this process." (PMID 39684286, 2024). "In addition, CASP8 and CTNNB1 managed to be in the top 3 lead hits identified via network pharmacology; CASP8 is found to be down-regulated in breast cancer due to promoter methylation." (PMID 38081857, 2023). "The dual function of PTCH1 as a multidrug efflux pump and a hedgehog receptor, and the active involvement of CTNNB1 in breast cancer strongly indicate that PTCH1 and CTNNB1 can be potential drug targets to overcome chemoresistance in ER +/HER2- breast cancer patients." (PMID 37700842, 2023). "CTNNB1 and EGFR are highly expressed in carcinomas such as lung and breast cancers." (PMID 36437827, 2022). "In contrast, genes often associated with the basal-like subtype and a poor prognosis such as MCL1, CTNNB1, EGFR, or SOX4 were found in the basal-like patient GSM519217 suggesting that the generated networks are capable of extracting breast cancer subtype-specific features." (PMID 33706810, 2021). "The highest levels of CTNNB1 are found in metaplastic carcinomas and non-metastasizing fibromatosis – two rare subsets of breast cancer." (PMID 32083079, 2020). "Given the presumed importance of WNT/CTNNB1 signaling in breast cancer stem cell maintenance, it is somewhat counterintuitive that the non-canonical co-receptor ROR1 is emerging as a potential key mediator of chemoresistance in breast cancer stem cells." (PMID 32083079, 2020). "At first, we examined the expression of Wnt/β-catenin signaling-related genes and found that expression levels of CTNNB1, LEF1, and TCF genes were significantly downregulated both in colon and breast cancers, which was confirmed by a TOP-/FOP-Flash reporter assay." (PMID 30650643, 2019). "Secondly, no or very few CTNNB1 mutations or CNA (especially the amplification and deletion) were observed in breast cancer, as well as the cell lines used in this study." (PMID 31462314, 2019). "It has been demonstrated that only 6% of breast cancers harbor mutations in the APC gene, and no mutations in CTNNB1 have been identified in breast cancer." (PMID 26124080, 2015). "In breast cancer, circNINL and circ_0008784 upregulation could indirectly affect Wnt/β-catenin activation through sponging miR-921 and miR-506–3p to promote ADAM9 and CTNNB1 (catenin beta 1) expression, respectively." (PMID 39524849, 2024).
breast carcinoma (continued). "In addition, other investigations have also linked mitochondrial activity to epithelial–mesenchymal transition in breast cancer, suggesting that the down-regulation of CDH1 and CTNNB1 in triple-negative breast tumors is correlated to a significant decrease in mitochondrial respiration." (PMID 36717859, 2023). "PTCH1 and CTNNB1 did not exhibit an increased risk in the control group and endocrine therapy group, further strengthening the predictive potential of PTCH1 and CTNNB1 in ER+/HER2- breast cancer." (PMID 37700842, 2023). "PIK3CA mutant ER+ breast cancers exhibit an RNA expression profile of enhanced Wnt/β-catenin signaling, including up-regulation of Wnt target genes (AXIN2, LEF1, MYCN) and other components such as transcriptional regulators (TCF7L1, TCF7L2, CTNNB1), receptors (FZD4, FZD7) and ligands (WNT5A)." (PMID 37471270, 2023). "Similar effects were also observed in canine mammary cancer cell lines that exhibit high basal Wnt/β-catenin activity, where treatment with dactolisib (dual pan-PI3Kα/γ/δ/β and mTOR inhibitor) enhanced TCF/LEF transcriptional activity, and CTNNB1 and AXIN2 mRNA expression." (PMID 37471270, 2023). "Unlike in breast cancer samples, Wnt activity determined by Axin2 was inversely correlated to YAP-mediated transcriptional activity in CRC samples, particularly in APC or CTNNB1 mutated cancer samples." (PMID 34298652, 2021). "We also examined the expression of these genes in a separate cohort of 698 luminal (ER/PR+) breast cancers using the TCGA dataset, where PIK3CA-mutant cancers displayed significantly higher expression of eight Wnt genes (LEF1, TCF7L1, TCF7L2, CTNNB1, LRP6, SFRP2, WNT5A, and MSX2)." (PMID 34035258, 2021). "Similarly, in other cancers, PIK3R1 downregulation has been proved to be an independent prognostic marker in breast cancers and to promote propagation, migration, epithelial–mesenchymal transition, and a stem-like phenotype in renal cancer cells through the AKT/GSK3beta/CTNNB1 pathway." (PMID 31119098, 2019). "Moreover, β-catenin (CTNNB1) was positively correlated with STT3 isoforms in TCGA breast cancer dataset (n = 1100) and nuclear active β-catenin levels were positively correlated with the protein expression levels of STT3 isoforms in breast cancer tissues (n = 129)." (PMID 29765039, 2018). "In summary, our study uncovered the existence of the miR-182-5p/CMTM7/CTNNA1/CTNNB1/TCF3 regulation loop in breast cancer, which may provide novel targets and promising strategies for breast cancer therapy." (PMID 36829181, 2023).